MS4A18 (membrane spanning 4-domains A18)
Tractability: Antibody: UniProt predicts a signal peptide or a membrane-spanning region; its Gene Ontology location is reachable by antibodies, with medium confidence.
Gene: Protein-coding gene on chromosome 11 (60,724,720 to 60,745,028, forward strand). Ensembl gene ENSG00000214782.
Subcellular location: Membrane
Gene Ontology:
Biological process: cell surface receptor signaling pathway
Cellular component: plasma membrane; membrane
Homologues: Orthologues: chimpanzee MS4A18 (99% identical), macaque MS4A18 (77% identical), rat Ms4a18 (46% identical), mouse Ms4a18 (45% identical), zebrafish ms4a17a.11 (17% identical), zebrafish ms4a17a.1 (17% identical), zebrafish ms4a17a.4 (17% identical), zebrafish ms4a17a.6 (17% identical), zebrafish ms4a17a.12 (17% identical), zebrafish si:ch73-56d11.5 (17% identical), zebrafish ms4a17a.10 (16% identical), zebrafish ms4a17a.5 (16% identical), and 17 more. Paralogues in human: MS4A8 (21% identical), MS4A12 (20% identical), MS4A15 (17% identical), MS4A4A (13% identical), MS4A1 (13% identical), MS4A3 (13% identical), MS4A14 (12% identical), MS4A10 (12% identical), MS4A6A (11% identical), MS4A4E (11% identical), MS4A7 (11% identical), MS4A5 (10% identical), and 4 more.
Diseases named in the same sentence as MS4A18 in open-access papers:
MS4A18 is named in the same sentence as 1 disease in open-access papers, as found by Europe PMC text mining. Sharing a sentence is not in itself a finding about the gene and the disease.
MS4A18 shares sentences with these, for which no sentence is quoted: glioma (1 paper).